TNF (tumor necrosis factor)
Diseases named in the same sentence as TNF in open-access papers (continued):
Sharing a sentence is not in itself a finding about the gene and the disease.
asthma (continued). "The absence, or reduced concentration of IL-10, associated with asthma enables the continued secretion of pro-inflammatory cytokines that contribute to lower airway inflammation, including IL-6, IL-5, IL-4, TNF-α, and IL-1." (PMID 31694631, 2019). "Some studies conducted on allergic rhinitis and asthma showed that there is an association of IL-4 with significant increase in TNF-α." (PMID 31871471, 2019). "Prenatal cytokine production (cord-blood concentrations of IL-4, IFN-γ, and tumor necrosis factor) was associated with the development of atopy and asthma at 6 years of age." (PMID 31507589, 2019). "TNFα has been implicated in asthma, with up-regulation of the TNFα axis noted in patients with severe refractory asthma." (PMID 31395050, 2019). "In contrast, obese asthma in adults is associated with increased airway and systemic inflammation, consistent with our observations of increased TNFα, IL-5, IL-33 and leptin concentrations in the BALF of dams fed the high fat diet." (PMID 30700289, 2019). "A polymorphism in the 5′ untranslated region of the TNF gene (G-308A), referred to as TNF-308 GG genotype, is associated with inflammatory diseases including asthma." (PMID 29576747, 2018). "We have also observed that among the cytokines that are implicated in asthma, TNF-α causes the greatest induction of CD38 expression in ASM cells." (PMID 29576747, 2018). "A meta-analysis study suggested that TNF polymorphisms were significantly associated with asthma susceptibility." (PMID 30473698, 2018). "Inflammatory cytokines such as IL-13 and TNF-α, which are implicated in asthma, augment CD38 expression and cADPR-mediated Ca2+ release and increase contractility of ASM." (PMID 29576747, 2018). "Another anti-TNF monoclonal antibodies, golimumab, demonstrated to be unsuitable for treatment in severe asthma when it shows unfavorable risk-benefit profile in a RCT." (PMID 30473698, 2018). "For this study, we focused on a moderate-to-severe asthma endotype that is neutrophilic and is associated with up-regulation of Tumor Necrosis Factor Alpha (TNF-α)." (PMID 28609485, 2017). "The present study is the first to show that a hypercoagulable state in asthma, characterized by enhanced plasma thrombin formation, is associated with increased blood levels of inflammatory cytokines, IL-6 and TNFα." (PMID 28429138, 2017). "We found BDR to be increased in participants reporting racial/ethnic discrimination and this association was limited to African American youth with TNF-α high asthma, an endotype thought to be resistant to traditional asthma medications." (PMID 28609485, 2017). "Recent studies have revealed that the extract of Ku-Shen suppresses both helper T cell 2 (Th2) and tumor necrosis factor-α (TNF-α) associated inflammation in murine asthma models." (PMID 28287417, 2017). "The association of P with asthma (Asthma + P) decreased (p <0.05) the TNF-α production when compared to its control group, the (Asthma) group." (PMID 29145431, 2017). "Our analysis indicated that multiple pathways were closely associated with asthma, such as TNF signaling pathway, PI3K-Akt signaling pathway, HIF-1 signaling pathway, and NF-κB signaling pathway." (PMID 29311942, 2017). "Upstream regulator analysis suggested that TNF was a highly significant molecular driver of the asthma-associated module." (PMID 26922672, 2016). "To mimic the inflammatory milieu in asthma we now examined the impact of OA (for 45 min) on IL-6 and IL-8 expression stimulated by TNFα – a pro-inflammatory cytokine implicated in asthma." (PMID 25985190, 2015). "Special attention was given to the role of TNFα which has been implicated in many aspects of airway pathology in asthma." (PMID 26494305, 2015). "The association of phthalate exposure and TNFα 5′CGI methylation with asthma was assessed in the last step." (PMID 25960783, 2015). "To analyze the association of TNFα 5′CGI methylation with asthma in CEAS cohort, we first compared mean methylation levels." (PMID 25960783, 2015).
asthma (continued). "TNFα has been implicated in airway inflammation and hyperresponsiveness and the regulation of immune cells, hallmark features of asthma." (PMID 25960783, 2015). "We demonstrated that higher exposure to phthalates is related to lower DNA methylation of TNFα, which in turn is associated with higher risk of asthma in children." (PMID 25960783, 2015). "In conclusion, we found that phthalate exposures are associated with DNA methylation and that methylation of TNFα in turn is associated with asthma." (PMID 25960783, 2015). "Methylation of the CpG site cg10717214 was negatively associated with asthma, when children had ‘AA’ or ‘AG’ genotype of the TNFα single nucleotide rs1800610." (PMID 25960783, 2015). "Tumour necrosis factor-α (TNF-α) is a proinflammatory cytokine that has been implicated in many aspects of the airway pathology in asthma." (PMID 26300589, 2015). "We determined the levels of 6 cytokines implicated in asthma, which can be divided by the response profiles Th1 (TNF-α and IL-6) and Th2 (IL-4, IL-13, IL-10, and IL-5)." (PMID 26101464, 2015). "Genetic variants of TNFα have been associated with development of asthma, total serum IgE level in asthma patients, and severity of asthma." (PMID 25960783, 2015). "Since the Taiwanese and the UK children have different genetic backgrounds, we additionally tested the TNFα single nucleotide polymorphism (SNP) rs1800610, an asthma candidate SNP." (PMID 25960783, 2015). "The results suggested that the TNF-α − 308G/A polymorphism contributes to susceptibility to asthma and, specifically, significantly elevated risks of asthma were associated with A allele carriers in the atopic population but not in the nonatopic population." (PMID 25759826, 2014). "More recently, it has been described that the genetic polymorphisms of TGF-β1 and TNF-α are associated with asthma." (PMID 25759826, 2014). "Using the combination of GWAS genotyping data, re-genotyping and imputation, they reported that TNF (rs1800629) was associated with asthma at a nominal significance level (0.035<p≤0.05)." (PMID 24936650, 2014). "We found that severe asthma exacerbation with V-D-deficiency showed increased TNF-α, NFκB expression and NFκB phosphorylation compared to that with 25-hydroxyvitamin D-sufficiency." (PMID 25380286, 2014). "The −308G/A polymorphism in the TNF-α gene has been extensively investigated for its association with asthma; however, the results of different studies have been inconsistent." (PMID 25759826, 2014). "In conclusion, this meta-analysis indicated that the TNF-α-308G/A polymorphism is significant associated with asthma." (PMID 24936650, 2014). "At last, there were 34 case-control studies in 32 articles concerning association between the TNF-α rs1800629 polymorphism and asthma risk." (PMID 24936650, 2014). "GSTP1 and TNF gene variants and associations between air pollution and incident childhood asthma: the traffic, asthma and genetics (TAG) Study." (PMID 24465030, 2014). "In our studies, serum TNF-α in V-D-deficiency in severe asthma exacerbation (n = 16) was significantly increased compared to that in V-D-sufficiency (n = 16) (p = 0.028)." (PMID 25380286, 2014). "The pooled OR was 1.46 (95% CI 1.21–1.76, P<0.0001), demonstrating a significant association between TNF-α rs1800629 polymorphism and asthma." (PMID 24936650, 2014). "The results indicated that TNF-α rs1800629 polymorphism was significantly associated with asthma risk in a recessive genetic model (OR = 1.46, 95% CI 1.21–1.76, P<0.0001)." (PMID 24936650, 2014). "Because secretion of cytokine is genetically regulated at the level of transcription, and the linkage of TNF-α polymorphisms with the genotype of asthma has been demonstrated in accumulating studies." (PMID 24936650, 2014). "The purpose of this study was to explore the association between the TNF-α rs1800629 (also refers as -308G/A) polymorphism and asthma susceptibility." (PMID 24936650, 2014).
asthma (continued). "Two years ago a meta-analysis was carried out to analyze the association between the −308G/A polymorphism of the TNF-α gene and asthma risk." (PMID 25759826, 2014). "Up to now, a lot of studies of genetic epidemiology have assessed the association of TNF-α gene polymorphisms and risk of asthma in different populations." (PMID 24936650, 2014). "Severe asthma exacerbation with V-D-deficiency increased TNF-α, NFκB expression and NFκB phosphorylation." (PMID 25380286, 2014). "The results indicated that LTA4H A-9188>G, TNFα G-308>A and IL-4Rα A1727>G polymorphisms were significantly associated with the development of difficult asthma in paediatric patients (p<0.001, p = 0.019 and p = 0.037, respectively)." (PMID 23573270, 2013). "In the present study, the G allele of TNFα G-308>A SNP conferred a significant risk of developing difficult asthma in children." (PMID 23573270, 2013). "Numerous other genes have been associated with asthma and related phenotypes, including those related to T helper cell (Th) pathways (IL-4, IL-13, IL-4Rα, TNFα and LTΑ)." (PMID 23573270, 2013). "TNF-α is a potent pro-inflammatory cytokine that favours granulocytes recruitment and which as been associated with asthma pathogenesis." (PMID 23555579, 2013). "The work shows that the carriers of genotypes, which are associated with higher TNF production, demonstrate more frequency of asthma, higher levels of neutrophil elastase, and decrease of bone density." (PMID 23343370, 2013). "IL-10 is produced by macrophages and by a subset of regulatory T cells (Tregs) and exerts its effects by inhibiting the synthesis of inflammatory cytokines (including asthma-associated cytokines such as TNF-α and IL-5) and gene presentation." (PMID 23781124, 2013). "TNFα is implicated in many aspects of asthma pathology, including development of airway hyperreactivity and attraction of eosinophils and neutrophils." (PMID 23533311, 2013). "The carriers of the TNF-α–308A allele more frequently had asthma as compared to patients homozygous for the TNF-α–308 G allele." (PMID 23343370, 2013). "The carriers of genotypes, which are associated with higher TNF-α production, demonstrated increased frequency of asthma, higher levels of neutrophil elastase, and decrease of bone density." (PMID 23343370, 2013). "NF-κB is a key transcriptional regulator of multiple pro-inflammatory mediators such as TNFα and interleukins, and enhanced activation of NF-κB has been implicated in asthma." (PMID 22439901, 2012). "TNF-α is a proinflammatory cytokine which has been implicated in many aspects of the airway pathology in asthma." (PMID 20735828, 2010). "In asthma we found a positive association of IL-4 with IL-5, and significant association with IL-13, TNF α as well as GM-CSF, while IL-5 is positively associated with IL-4, IL-10 and GM-CSF." (PMID 20616938, 2010). "Among them, seven polymorphisms (ADAM33 T1-C/T, ACE D/I, FcεRIβ -6843G/A, IL-13 -1923C/T, IL-13 -2044A/G, RANTES -28C/G and TNF-α -308G/A) were statistically associated with increased risk of asthma." (PMID 20868478, 2010). "Consistently, we found the TNF-α-308A/G polymorphism was significantly associated with increased risk of asthma (OR = 1.36, 95%CT = 1.13-1.63 for AA+AG vs. GG) in Chinese population." (PMID 20868478, 2010). "This pro-inflammatory cytokine is capable of causing the release of other pro-inflammatory cytokines, such as IL-8, tumor necrosis factor alpha (TNFα), and GM-CSF, which have been associated with asthma in murine models, in humans, or with disease severity." (PMID 21179211, 2010). "Because the fixed-effect model is more precise than random effect model, the strength of evidence of ADAM33 T1-C/T, ACE D/I, IL-13 -1923C/T, RANTES -28C/G, as risk factors for asthma was greater than that of FcεRIβ -6843G/A, IL-13 -2044A/G and TNF-α -308G/A." (PMID 20868478, 2010).
asthma (continued). "After subgroup analysis by age, the ACE D/I, β2-Adrenergic Receptor (β2-AR) -79G/C, TNF-α -308G/A, Interleukin 4 receptor(IL-4R) -1902G/A and IL-13 -1923C/T polymorphisms were found significantly associated with asthma risk in Chinese children." (PMID 20868478, 2010). "The TNF-α gene, encodes a key proinflammatory cytokine in airway, is located on an asthma susceptible region-chromosome 6p." (PMID 20868478, 2010). "TNF-α is prominent in asthmatic airways and genotypes that correlate with increased TNF-α secretion are associated with an increased risk of asthma." (PMID 18724870, 2008). "Previous studies from our laboratory showed that CD38 expression and its enzymatic activities are augmented by TNF-α and IL-13, cytokines that are implicated in the pathogenesis of inflammatory airway diseases such as asthma." (PMID 18341691, 2008). "Nerve growth factor, which is closely associated with asthma, is released from lung fibroblasts at an increased rate when exposed to TNF-α and IL-1β." (PMID 21157520, 2008). "The GSTP1 114Val allele also had a suggestive association with increased risk of persistent wheezing, and TNF-308A with asthma and persistent wheezing (p < 0.05 unadjusted)." (PMID 18709160, 2008). "We also examined the association of LTA and TNF individual SNPs and haplotypes with asthma stratified by exposure to a smoking parent before child turned two because exposure in early childhood has also been consistently associated with childhood asthma risk." (PMID 17450233, 2007). "The TNF-238, TNF-857, and TNF-1031 polymorphisms gave weaker, and more unstable, evidence of association with asthma." (PMID 17450233, 2007). "Among all cases, individuals carrying one copy of the ht5 (CGTCAG) haplotype, containing the TNF-308A allele, exhibited an increased risk of asthma of borderline statistical significance (RR = 1.45; 95% CI, 0.97–2.19)." (PMID 17450233, 2007). "For TNF, carrying at least one copy of the TNF-308A allele was associated with increased asthma risk [relative risk (RR) = 1.54; 95% confidence interval (CI), 1.04–2.28; p = 0.031; false discovery rate = 0.12] relative to homozygotes for the major G allele." (PMID 17450233, 2007). "The A allele of the TNF-308 SNP was associated with increased risk of asthma [relative risk (RR) = 1.54; 95% confidence interval (CI), 1.04–2.28], especially among children of non-smoking parents (RR = 2.06; 95% CI, 1.19–3.55; p for interaction = 0.09)." (PMID 17450233, 2007). "Recent meta-analyses report modest associations between single nucleotide polymorphisms (SNPs) in TNF (encoding TNF-α) and increased risk for asthma, system lupus erythamatosus (SLE), and psoriatic arthritis." (PMID 17940599, 2007). "The TNF-308 polymorphism has been frequently studied in asthma and atopy association studies because it has direct functional effects on TNF gene regulation." (PMID 17450233, 2007). "Of the various pulmonary diseases, TNFα is implicated in asthma, chronic bronchitis (CB), chronic obstructive pulmonary disease (COPD), acute lung injury (ALI) and acute respiratory distress syndrome (ARDS)." (PMID 17034639, 2006). "TNF signaling has been implicated in airway hyperresponsiveness and airway inflammation in asthma." (PMID 41427379, 2025). "A variety of additional mediators, such as TNF-α and IL-17, have been implicated in the pathogenesis of asthma by promoting the release of pro-inflammatory molecules and chemotactic signals that facilitate immune cell recruitment and contribute to airway remodeling." (PMID 40565216, 2025). "Other studies, however, have shown a strong correlation between maternal and cord blood IFNγ concentrations and that detectable cord blood concentrations of IFNγ are associated with a lower risk of asthma and atopy at age 6 years, and detectable cord blood TNF‐α with a lower risk of atopy." (PMID 40714954, 2025).
asthma (continued). "Furthermore, different studies have shown that Mg2+ can interfere with the activation of NF-κB, a central pathway in the transcription of proinflammatory genes, such as TNF-α, IL-4, IL-5, and IL-13, all of which are implicated in asthma pathophysiology." (PMID 40868515, 2025). "In addition, asthma conditions have been linked to increased levels of inflammatory cytokines such as IL-4, IL-5, IL-17, IL-13, and TNF-α in addition to decreased IFN-γ and IL-10." (PMID 39295946, 2024). "Collectively, these findings demonstrate that specifically targeting the TNF–TNFR2 axis (as opposed to the TNF–TNFR1 axis) may be a novel therapeutic avenue for asthma and could reduce adverse effects associated with pre-existing anti-TNF agents." (PMID 38540714, 2024). "Persistently elevated TNF-α responses and higher plasma TNF-α levels in infancy may be a biomarker predicting persistent wheezing, while higher bronchial lavage TNF-α has been associated with the pathogenesis of asthma in adults." (PMID 39683596, 2024). "Similarly, the TNF signaling pathway has been implicated in both the inflammatory and structural aspects of asthma." (PMID 39850030, 2024). "Hence, the individual risk/benefit assessment should be considered for each asthma patient before using TNF-blockers." (PMID 37199256, 2023). "In terms of inflammatory cytokines, ATG5 was positively associated with TNF-α (rs=0.247, P < 0.001), IL-1β (rs=0.233, P = 0.001), IL-6 (rs=0.213, P = 0.003), and IL-17 (rs=0.154, P = 0.029) in adult asthma patients." (PMID 37644509, 2023). "TNF is a protein-coding gene that is associated with malaria and asthma." (PMID 37239981, 2023). "Increased sputum TNFα levels are associated with severe asthma exacerbations." (PMID 36760534, 2023). "Moreover, epigenetic loci modified by albuterol were located in genes enriched in asthma-associated processes (i.e., TNF-α, NF-kB, and IL-2 signaling pathways) and likely regulated by a potential asthma drug (i.e., TSA)." (PMID 37784136, 2023). "Moreover, simultaneous administration of IL-6 and TNF inhibitors more effectively protects the lungs from asthma-associated tissue remodeling." (PMID 35408882, 2022). "In the context of allergic airway inflammation, both TNF and IL-6 overproduction may trigger different inflammatory pathways implicated in asthma pathogenesis." (PMID 35408882, 2022). "Moreover, anti-TNF causes exacerbations of asthma, bronchospasm, or wheezing, although most of these have been related to anaphylaxis." (PMID 35163689, 2022). "The study explored the influence of the interaction between genes and environmental factors on children with asthma observed that children with asthma who carry the TNF-308 GG gene have a significantly lower risk of bronchial symptoms under low ozone exposure (OR: 0.53, 95% CI: 0.31–0.91)." (PMID 35450107, 2022). "In vitro, miR874, which may be associated with the development of asthma, has been shown to inhibit TNF-α-induced IL-6, IL-8, collagen I, and collagen III production in ASM cells." (PMID 35626330, 2022). "In mice HDM-induced severe asthma a combination of TNF and IL-6 inhibitors prevented IL-6-dependent eosinophilia as IL-6 neutralization helped to suppress the pathological side effects associated with systemic TNF neutralization." (PMID 34084159, 2021). "The hypothesized mechanism causing this phenotype of asthma is a macrophage-dependent inflammation of the adipose tissue resulting in a pronounced release of IL-6, TNF-α, and leptin that can be reversed with a weight loss." (PMID 35055325, 2021). "Phthalate exposure could also attenuate the methylation level of TNF-α in whole blood white blood cells and lead to its upregulation, which is an event that increases the risk of asthma in children." (PMID 33781317, 2021). "TNF polymorphisms, thought to affect the expression of pro-inflammatory cytokines, seem to influence the response of the lungs to O3, and the risk of developing asthma." (PMID 32867076, 2020).